GADD45B (growth arrest and DNA damage inducible beta)
Diseases named in the same sentence as GADD45B in open-access papers (continued):
Sharing a sentence is not in itself a finding about the gene and the disease.
melanoma (9 papers, 2019 to 2025). A malignant, usually aggressive tumor composed of atypical, neoplastic melanocytes. "In order to study the relation between GADD45B mutation and melanoma, multi-omics data of 473 patients in TCGA database were analyzed." (PMID 31681565, 2019). "It was hypothesized that, once melanoma formed, caused by cancer's self-defense, GADD45B would be down-regulated because of its tumor suppression." (PMID 31681565, 2019). "Although Gadd45b is supposed to be linked with melanoma, the mechanism has yet to be clarified." (PMID 31681565, 2019). "On the other hand, the expression of one selected marker, GADD45B, plays a critical role in the melanoma cell cycle." (PMID 39763976, 2024). "In malignant melanoma, GADD45B played a crucial role as an anti-tumor response participant by regulating the immune response of Th1 cells and CD8+ T cells." (PMID 37608794, 2023). "In a mouse model, out of 73 genes involved in melanocyte progression to melanoma cells after a UV dose, there was inhibition of GADD45B." (PMID 36982460, 2023). "In our previous study on melanoma, GADD45B, a key protein regulating melanoma development was screened with miR-300, an upstream regulatory element." (PMID 38070141, 2023). "Coincidentally, the expression of Gadd45b is increased drastically in B16 melanoma cells treated with HA." (PMID 36311022, 2022). "The TFs that regulate miR-300 and GADD45B also correlate with immune cell infiltration, which is one of the main indicators and physiological responses to melanoma." (PMID 31681565, 2019). "As the only differential gene in the melanoma pathway, GADD45B severely affects the prognosis of melanoma patients." (PMID 31681565, 2019). "In summary, we suspect that miR-300 would be increased in melanoma cells and exosomes, thereby upregulating GADD45B in keratinocytes and melanoma cells, protecting melanoma against ROS." (PMID 31681565, 2019). "GADD45B is a key factor in melanoma, and once alteration appeared, the prognosis of patients becomes worse." (PMID 31681565, 2019). "In melanoma, whether GADD45B can regulate tumor growth through cell proliferation, cycle apoptosis migration and other functions needs further confirmation." (PMID 38070141, 2023). "Gadd45b expression is upregulated by interleukin-12 (IL-12), which increases TCR-triggered activation of p38 MAP kinase and thus encodes a key signaling protein required for effective anti-melanoma immune responses." (PMID 36311022, 2022). "In addition to several ECM proteins that were found to be downregulated we also observed upregulation of several pro-apoptotic genes such as BAX, CDKN1A, GADD45A, GADD45B, etc. in TP-472–treated melanoma cells." (PMID 34771678, 2021). "However, studies about GADD45B and melanoma are very infrequent, and the mechanism is still unclear." (PMID 31681565, 2019). "Accordingly, regulation of GADD45B may become a significant methodology to prevent melanoma formation." (PMID 31681565, 2019). "Thus, the relevance of investigating the role of Gadd45b in oxidative stress-induced melanoma oncogenesis." (PMID 31681565, 2019). "After analyzing the relation between GADD45B and melanoma according to TCGA database, it was also confirmed that gene features of GADD45B might correlate with poor prognosis." (PMID 31681565, 2019). "After analysis of DEGs and DEMs, it was supposed that miR-300 and GADD45B might regulate melanoma development." (PMID 31681565, 2019). "The results showed that the specific TFs might interact with miR-300/GADD45B in melanoma progression." (PMID 31681565, 2019). "Therefore, it was supposed that in UV irradiated keratinocytes of melanoma patients, Gadd45b would be up-regulated, given the lower level miR-300." (PMID 31681565, 2019). "Therefore, it was suggested that miR-300 may promote cell cycle progression in melanoma via GADD45B." (PMID 38070141, 2023).
melanoma (continued). "Interestingly, in our previous study, it was confirmed that in melanoma, the miR-300 could regulate the expression of GADD45B which would also mediate cell cycle pathway." (PMID 38070141, 2023). "MiR-300 may also play a significant role in melanoma via inhibiting GADD45B expression." (PMID 31681565, 2019). "Thus, we believe GADD45B may be a key factor in the regulation of melanoma against oxidative stress and DNA damage." (PMID 31681565, 2019). "It demonstrated that the status of GADD45B might be involved in melanoma development." (PMID 31681565, 2019). "Moreover, GADD45B had lower level in melanoma compared with normal melanocytes." (PMID 31681565, 2019). "In melanoma, GADD45B could interact with other genes like STAT3." (PMID 31681565, 2019). "To further investigate the impact of GADD45B on SKCM, we performed in vitro experiments using human malignant melanoma cell lines." (PMID 40350499, 2025).
lung carcinoma (7 papers, 2016 to 2025). "In this study, transcriptome profiling and RT-qPCR validation revealed that PGL arrests the cell cycle via downregulation of the expression of RB1, CCNH, MDM2, ACCN4, CCND2, GADD45A, and GADD45B in lung cancer cells." (PMID 27355352, 2016). "✓ Aberrant methylation at the promoter region of RASSF1A and GADD45β inversely correlates with protein expression and is linked to the acquisition of TKI resistance in lung cancer cells.✓ Cell treatment with 5-Aza-CdR could partially restore the sensitivity of cells to EGFR-TKI." (PMID 37152062, 2023).
ovarian carcinoma (7 papers, 2010 to 2025). A malignant neoplasm originating from the surface ovarian epithelium. "Additionally, GADD45B overexpression has been found to enhance the migration of ovarian cancer cells and is closely linked to ovarian cancer metastasis." (PMID 37608794, 2023). "GADD45B is a growth arrest and DNA-damage-inducible beta gene known as a prognostic biomarker in colorectal adenocarcinoma and a facilitator of metastasis in ovarian cancer through epithelial–mesenchymal transition." (PMID 37746266, 2023).
depression (5 papers, 2021 to 2026). "In the Flinder Sensitive Line (FSL) genetic rat model of depression, untreated rats exhibited a decrease in GADD45β mRNA levels in the prefrontal cortex." (PMID 38332860, 2024). "In unpredictable chronic mild stress (UCMS) mice, a model for depression, the expression of Gadd45b was down-regulated in the hippocampus by the growth factor β (TGF-β) signaling pathway." (PMID 36311022, 2022). "Gadd45b intervenes in depression by modifying the DNA methylation levels of GAD67, recombinant neurotrophic tyrosine kinase receptor type 2 (Ntrk2), neurturin, and distal-less homeobox 5 (Dlx5)." (PMID 36311022, 2022). "Presently, the clinical effect of Gadd45b in the treatment of depression remains contentious and requires additional investigation in future trials." (PMID 36311022, 2022). "They determined that Gadd45b could play a role in neuronal remodeling activity-related neurogenesis in the hippocampus of adult rats, alleviating poststroke depression through the BDNF signaling pathway." (PMID 36311022, 2022). "Likewise, in the Flinders Sensitive Line (FSL) genetic rodent model of depression, an observed trend of decreased Gadd45b mRNA levels in these hypermethylated untreated rats is consistent with the demethylating function of Gadd45b in the adult brain." (PMID 36311022, 2022). "Collectively, these findings indicate that Gadd45b could be a novel mediator of depression-like behaviors." (PMID 36311022, 2022). "Accordingly, Gadd45b, generated by ECT, at least in part mediates the therapeutic benefits of ECT on depression." (PMID 36311022, 2022). "The analysis of mRNA expression in the prefrontal cortex of suicide victims with major depressive disorder revealed a differential profile with 27 downregulated mRNAs, including HSPA1A, HSPA1B, DNAJB1, NR4A1, and GADD45B, which are involved in proteostasis, transcriptional regulation, and apoptosis." (PMID 41977312, 2026).
ischemic stroke (5 papers, 2021 to 2025). A stroke disorder caused by obstruction of blood flow to the brain, due to thrombotic (local blood clot formation) or embolic (due to a blood clot or other material traveling from another site) event. "Leveraging multiple bioinformatic approaches, we pinpointed a critical gene signature within the ERK pathway—termed GSERK—that prominently included GADD45A, DUSP1, and GADD45B as central modulators implicated in ischemic stroke pathogenesis." (PMID 40636523, 2025). "Our integration of multiple complementary machine-learning methods, like Boruta, SVM, LASSO, and random forest, provided rigorous confirmation of GADD45A, DUSP1, and GADD45B as robust biomarkers for ischemic stroke, substantially minimizing the risk of false discoveries inherent in genomic analyses." (PMID 40636523, 2025). "The ROC curve analysis in the total sample set revealed moderate discriminatory capacity for DUSP1 (AUC = 0.75), GADD45A (AUC = 0.72), and GADD45B (AUC = 0.70), suggesting these genes may serve as potential diagnostic biomarkers for ischemic stroke." (PMID 40636523, 2025). "Collectively, these results support the potential of DUSP1, GADD45A, and GADD45B as useful biomarkers for ischemic stroke, warranting further clinical validation." (PMID 40636523, 2025). "Using this approach, we identified a distinct gene signature—termed GSERK—including GADD45A, DUSP1, EREG, IL1B, JUN, and GADD45B as central regulatory nodes within ischemic stroke-related co-expression networks." (PMID 40636523, 2025). "Growth arrest and DNA-damage-inducible protein 45 β (Gadd45b) is associated with subventricular zone (SVZ) neurogenesis after ischemic stroke, and Gadd45b mediates enriched environment-induced SVZ neurogenesis via BDNF." (PMID 37484824, 2023). "GADD45B was upregulated in ischemic stroke and could attenuate cerebral ischemia-induced neuronal apoptotic death and axonal plasticity." (PMID 37511062, 2023). "Taken together, Gadd45b is a new putative target for ischemic stroke." (PMID 36311022, 2022).
leukemia (5 papers, 2014 to 2022). A malignant (clonal) hematologic disorder, involving hematopoietic stem cells and characterized by the presence of primitive or atypical myeloid or lymphoid cells in the bone marrow and the blood. "Ectopic expression of Gadd45b enhanced stress mediated apoptosis in both M1 leukemia and H1299 lung carcinoma cells." (PMID 30279966, 2018). "Clearly, it was of interest to examine the possible role of Gadd45b in modulating BCR-ABL driven leukemia." (PMID 30279966, 2018). "Gadd45β can also act as a stress sensor in the development of hematopoietic malignancies like leukemia." (PMID 27507053, 2016). "Finally, it would be of interest to explore if overexpression of Gadd45a delays leukemia development, and whether other Gadd45 proteins (GADD45B and GADD45G) either separately or in combination with Gadd45a modulate CML development." (PMID 28086219, 2017).
liver cancer (5 papers, 2012 to 2024). An epithelial or non-epithelial malignant neoplasm that arises from the liver. "The data shows that GADD45B expression levels decreased according to liver cancer stage progression." (PMID 37746289, 2023). "Purpose of this study was to explore the effect of Gadd45β on the apoptosis of liver cancer cells, and the possible mechanism was examined." (PMID 29225771, 2017). "The quantitative analysis showed that Gadd45β mRNA level in liver cancer tissue were readily lower than that in peri-tumor tissues (**P < 0.01; ***P < 0.001)." (PMID 29225771, 2017). "Methylation mediated Gadd45β expression inhibited the stemness of liver cancer cells, promoting the chemotherapy-induced apoptosis." (PMID 29225771, 2017). "In this study, we first confirmed the decreased expression of Gadd45β in human liver cancer tissues and human liver cancer cell lines, when compared to the peri-tumor liver tissue and normal liver cells." (PMID 29225771, 2017). "Finally, to assess the effect of Gadd45β proteins on the apoptosis of liver cancer cells, cell viability assay was further used to assess the degree of apoptosis of cells with different treatment." (PMID 29225771, 2017). "And the mechanism may depend on the inhibition of stemness of liver cancer cells induced by induction of Gadd45β." (PMID 29225771, 2017). "In this study, the role of Gadd45β in the apoptosis of liver cancer cells was studied." (PMID 29225771, 2017). "Therefore, we concluded that Gadd45β overexpression inhibited the stem cell properties of liver cancer cells, enhancing the chemosensitivity." (PMID 29225771, 2017). "Furthermore, Gadd45β inhibited the stemness properties of liver cancer cells, enhancing the chemosensitivity of liver cancer cells." (PMID 29225771, 2017). "And, it was found that Gadd45β could inhibit the stemness of liver cancer cells, enhancing the apoptosis of cancer cells induced by chemotherapy." (PMID 29225771, 2017). "Furthermore, the tested liver cancer cell lines also showed a lower expression of Gadd45β, when compared to normal liver cell." (PMID 29225771, 2017). "This suggested us that Gadd45β may play an important role in the stemness of liver cancer cells." (PMID 29225771, 2017). "In this study, it was found that Gadd45β methylation was correlated with their expression in HCC tissues and liver cancer cell lines." (PMID 29225771, 2017). "Gadd45β expression in HCC is reduced and gradually decreases with the progression of liver cancer." (PMID 39653679, 2024). "Thus, the elucidation of the detailed molecular mechanistic roles played by GADD45β and FNDC5 in liver cancer will contribute to finding new therapeutic targets." (PMID 37746289, 2023). "the expression of Gadd45β was repressed in HCC tissues and liver cancer cells, and the Gadd45β methylation may influence the expression." (PMID 29225771, 2017).
non-small cell lung carcinoma (5 papers, 2016 to 2025). A group of at least three distinct histological types of lung cancer, including non-small cell squamous cell carcinoma, adenocarcinoma, and large cell carcinoma. "A prognostic risk index, grounded on four persister genes (LYNX1, SYNPO, GADD45B, and PDLIM1), was constructed in non-small-cell lung cancer patients from The Cancer Genome Atlas Program (TCGA) using stepwise Cox regression analysis." (PMID 33330109, 2020). "AP-2γ inhibits GADD45B expression, with overexpressed TFAP2C suppressing GADD45B and PMAIP1 at both mRNA and protein levels in non-small cell lung cancer cells." (PMID 41373739, 2025).
rheumatoid arthritis (5 papers, 2019 to 2023). A chronic, systemic autoimmune disorder characterized by inflammation in the synovial membranes and articular surfaces. "Furthermore, mRNA expression of GADD45β was associated with cytokine production and T helper cell differentiation and a genetic polymorphism study indicated a role for GADD45β in rheumatoid arthritis and lupus." (PMID 34867947, 2021). "Polymorphisms in GADD45a and GADD45b genes and protein expression have been investigated in rheumatoid arthritis (RA) and systemic lupus erythematosus (SLE) patients." (PMID 34272424, 2021). "This study is to examine the associations of GADD45a and GADD45b genes with rheumatoid arthritis (RA) and systemic lupus erythematosus (SLE) patients." (PMID 31195707, 2019). "For example, the Gadd45b mRNA is expressed at lower levels in patients with rheumatoid arthritis (RA) than in healthy people." (PMID 36311022, 2022). "In the synovial fluid of rheumatoid arthritis, high GADD45B expression enhances Th1 cell survival." (PMID 37511062, 2023).
cardiac hypertrophy (4 papers, 2018 to 2025). "Three genes linked to inhibition of cardiac hypertrophy were upregulate, viz., DKK3 (Dickkopf-3), FBXO32 (encoding E3 ligase, Fbxo32), and GADD45B, which blocks MKK7-induced JNK activation." (PMID 29556499, 2018). "Among them, those coding for DUSP family members, CDKN1A, BTG2, GADD45B,34, and MCL-1 have been previously shown to be upregulated in human myocardial tissues in response to stress and/or DNA damage and to play a role in the regulation of cardiac hypertrophy and remodeling in animal models." (PMID 31924244, 2020).